RNU7-152P (RNA, U7 small nuclear 152 pseudogene)
Gene: Small nuclear RNA gene on chromosome 6 (155,654,963 to 155,655,026, reverse strand). Ensembl gene ENSG00000238789.
Homologues: Orthologues: chimpanzee U7 (100% identical), macaque U7 (94% identical). Paralogues in human: RNU7-35P (83% identical), RNU7-73P (83% identical), RNU7-167P (81% identical), RNU7-187P (81% identical), RNU7-7P (81% identical), RNU7-82P (81% identical), RNU7-19P (80% identical), RNU7-70P (80% identical), U7 (80% identical), RNU7-113P (78% identical), RNU7-124P (78% identical), RNU7-128P (78% identical), and 141 more.